RNU1-132P (RNA, U1 small nuclear 132, pseudogene)
Gene: Small nuclear RNA gene on chromosome 1 (245,133,927 to 245,134,090, reverse strand). Ensembl gene ENSG00000201170.
Homologues: Orthologues: chimpanzee U1 (97% identical), macaque U1 (90% identical), mouse Gm24032 (77% identical), rat LOC120101383 (73% identical), guinea pig U1 (68% identical). Paralogues in human: RNVU1-7 (83% identical), RNU1-1 (82% identical), RNU1-2 (82% identical), RNU1-27P (82% identical), RNU1-28P (82% identical), RNU1-3 (82% identical), RNU1-4 (82% identical), RNVU1-18 (82% identical), RNVU1-29 (82% identical), U1 (82% identical), RNU1-78P (82% identical), RNU1-89P (82% identical), and 134 more.